CD68 (CD68 molecule)
Diseases named in the same sentence as CD68 in open-access papers (continued):
Sharing a sentence is not in itself a finding about the gene and the disease.
breast carcinoma (continued). "We assessed CD74 and MHCII expression in tumor cells, as well as CD8, CD4, and CD68 tumor infiltrating leucocyte (TIL) density by immunohistochemistry in a cohort of 492 breast cancer patients." (PMID 27058619, 2017). "CD68-positive cells were detected in all breast cancer cases examined in this study (median number of CD68-positive cells = 150, range: 5–1237)." (PMID 28103902, 2017). "Immunofluorescent/confocal microscopy analysis of distribution of CD68 and stabilin-1 in human breast cancer samples of all stages demonstrated presence of three cell subpopulations: CD68+Stab-1−, CD68−Stab-1+, and CD68+Stab-1+." (PMID 27105498, 2016). "It is therefore of note that immunohistochemical staining for the monocyte/macrophage marker CD68 revealed a breast cancer subtype-specific distribution of macrophages within the 129 breast cancer samples used in this study." (PMID 27713152, 2016). "For example, in human breast cancer a CD68 high/CD4 high/CD8 low T-cell signature is significantly correlated with reduced patient survival." (PMID 25884510, 2015). "Infiltration of CD68+ macrophages correlated with poor OS, suggesting the enrichment of macrophage is predictive of poor prognosis and reduced survival in human breast cancer." (PMID 25685069, 2015). "Another breast cancer cohort study (n = 144), looking at total macrophage number (CD68+) and M2 macrophages (CD163+) found that CD163 was also associated with other prognostic markers." (PMID 26243145, 2015). "Considering that the angiogenesis is intense just after adipose tissue grafting or translocation, what represents one among many theories for its potential for breast cancer, a chronic higher concentration of CD68-labelled macrophage was expected." (PMID 26101731, 2015). "CD163 expression by breast cancer cells is related to early distant recurrence and reduced survival time, and breast cancer cells expressed CD68." (PMID 26267609, 2015). "To confirm that macrophage infiltration is associated with poor prognosis in primary breast cancer, we analysed the expression of CD68 protein within a tissue microarray (TMA) containing formalin fixed tumours from 129 breast cancer patients." (PMID 26008983, 2015). "We also assessed CD68 mRNA expression in a cohort of 1107 breast cancer tumour tissue samples (containing tumour stroma) comprising six publically available gene expression data sets." (PMID 26008983, 2015). "We previously demonstrated that peritoneal and tumor-associated macrophages from mammary tumor-bearing mice exhibit decreased mean fluorescent expression (MFI) of myeloid differentiation markers F4/80, CD11b, CD68 and CD115 (MCSF receptor) yet upregulate Gr-1." (PMID 25599228, 2015). "More importantly, CD68 in the tumor stroma was an independent prognostic factor for reduced breast cancer specific survival." (PMID 24883329, 2014). "We analyzed pre- and post-treatment tumor-infiltrating immune cells (CD3, CD4, CD8, CD20, CD68, Foxp3) by immunohistochemistry in a series of 121 breast cancer patients homogeneously treated with neoadjuvant chemotherapy." (PMID 25432519, 2014). "IHC with antibodies to Igγ, CK, CD20 and CD68 was carried out on serial sections of breast cancer tissue (invasive ductal carcinoma) (a1–4)." (PMID 23554916, 2013). "We performed an immunohistochemical study counting CD3, CD20 and CD68 positive cells at the invasive front, in 102 breast carcinomas." (PMID 23300781, 2012). "CD163+ and CD68+ cells with a macrophage-morphology were present in both TS and TN of primary breast cancers." (PMID 22824040, 2012). "Kaplan Meier analysis and Cox proportional hazards modeling were used to assess the impact of CD163+ and CD68+ myeloid cells in tumor stroma and tumor nest, respectively, on recurrence free survival, breast cancer specific and overall survival." (PMID 22824040, 2012).
breast carcinoma (continued). "Further studies will be necessary to assess if this CD68/(CD3+CD20) ratio at the invasive front can contribute to identify patients with breast cancer candidates to different therapeutic strategies based on immuno-modulation." (PMID 23300781, 2012). "CD163+ and CD68+ macrophages were more equally distributed among the patients with luminal A breast cancer." (PMID 22824040, 2012). "More importantly, CD68 in tumor stroma was an independent prognostic factor for reduced breast cancer specific survival." (PMID 22824040, 2012). "We also analyzed the prognostic value of the localization of CD163+ and CD68+ myeloid cells in human breast cancer." (PMID 22824040, 2012). "The extent of infiltrating CD163+ or CD68+ myeloid cells in tumor nest versus tumor stroma was evaluated by immunohistochemistry in tissue microarrays with tumors from 144 breast cancer cases." (PMID 22824040, 2012). "Dense infiltration of CD68+ macrophages in the TS positively correlated with large tumor size and high grade and inversely correlated with luminal A breast cancer." (PMID 22824040, 2012). "CD68+ macrophages in tumor stroma positively correlated to tumor size and inversely correlated to luminal A breast cancer." (PMID 22824040, 2012). "According to our data, triple-negative/basal-like breast cancers seem to harbor more CD163+ than CD68+ cells within the TS." (PMID 22824040, 2012). "Although the prognostic significance of TAMs in TCCRP remains undefined, the presence of a CD68+/CD163+ macrophage infiltrate, a signature associated with adverse features in broader breast cancer cohorts, was considered a potential high-risk factor in this individual case." (PMID 41256322, 2025). "In addition, multiplex IF staining of human liver metastases of breast cancer confirmed the correlation of NETs with CD68+ cells, DMBT1 and CCL8 expression." (PMID 40796724, 2025). "Breast carcinoma tissue was analyzed by Cobas PIK3CA mutation test for the presence of PIK3CA mutation and immunohistochemistry was applied to assess PD-L1 expression and CD4, CD8, CD68, and CD163 infiltration within tumor." (PMID 41096755, 2025). "Single-cell analysis in breast cancer has revealed that SPP1-positive tumor-associated macrophages (TAMs) display significantly increased expression of markers like apolipoprotein E (APOE), CD204, CD68, and CADM1." (PMID 39727934, 2024). "These experimental observations may support our findings that CD47 and CD68 combined are strongly related to both lymphatic and blood vessel invasion in breast cancer." (PMID 36598153, 2023). "Importantly, CD68+ cells in TLSs served as an independent prognosticator of locoregional recurrent breast cancer." (PMID 38133211, 2023). "Previous studies have demonstrated that CD163+ macrophages in the tumour stroma of breast cancer tissues correlated to high tumour grade, larger tumour size, triple negative cancers, and suggest that CD68+ macrophages in the tumour stroma is an independent prognostic marker for cancer free survival." (PMID 37108548, 2023). "Moreover, in the ER− locoregional recurrent breast cancer, TLSs, and immune cells (CD3+, CD68+, and CD38+) within TLSs were associated with improved PFS." (PMID 38133211, 2023). "In breast cancer, MMP11 expression was considered as a biomarker for prognosis, and correlated with a high CD68/(CD3 + CD20) ratio in CD68+ macrophages, which caused the polarisation of macrophages in the tumour centre, resulting in a higher metastatic phenotype." (PMID 36683048, 2023). "The quantitative analysis of the average fluorescence intensity of SIPA1 and the ratio of CD68-positive cells in the tumour milieu revealed that the expression level of SIPA1 in breast cancer positively correlated with the ratio of infiltrated macrophages in invasive ductal carcinoma samples." (PMID 35453742, 2022).
breast carcinoma (continued). "Moreover, examination of PYK2 protein expression in human breast cancer sections by IF analysis confirmed the expression of PYK2 protein in both breast cancer cells (Cytokeratin 8‐positive) and TAMs (CD68 positive)." (PMID 35092356, 2022). "In addition, signature scores representing macrophages were higher in DDIR-positive tumours (P < 0.001), and this finding was confirmed across breast cancer subtypes with immunohistochemical staining for CD68." (PMID 34728791, 2022). "This implies that the interaction of Wnt7b and FZD4 between ATMs (CD68+) and adipocytes (FCs) may contribute to the poor prognosis of breast cancer, mainly in the form of a high BCPRS profile." (PMID 34457116, 2021). "Dannenberg and colleagues have previously studied CD68 + CLS-B in breast cancer patients, reporting a pilot study (N = 30) which showed a CD68 + CLS-B prevalence of 50%5, and a subsequent cross-sectional sample (N = 100) which showed a CD68 + CLS-B prevalence of 52%15." (PMID 34294716, 2021). "We have shown that CLS-B, whether found on H&E histologic sections (hCLS-B) or as previously reported, using the pan-macrophage marker CD68, occur frequently in breast adipose tissue of breast cancer patients (seen in 36% and 31% of patients, respectively)." (PMID 34294716, 2021). "There was indeed an increase in the CD68 + macrophage population in breast cancer tissues." (PMID 33937269, 2021). "In addition, reduced recurrence-free survival was associated with increased stromal CD68+ CD163+ TAMs in basal-like breast cancer, and with increased tumor center CD68+ CD163+TAMs in colorectal cancer." (PMID 34988021, 2021). "In addition, CD68+ macrophage infiltration in the hollow regions of mammary tumors in the IT group were also seen to be greater than that in the INT group." (PMID 34164110, 2021). "In addition, CD68+ macrophage infiltration was found in mammary tumors of the INT and IT groups, particularly in necrotic areas and hollow regions (respectively)." (PMID 34164110, 2021). "As we showed, analysis of the TCGA database revealed a prognostic role of TGFβR1 and p-Smad2 in the overall survival of breast cancer patients, and examination of breast cancer tissue samples indicated the proximity of macrophage marker CD68 and p-Smad2 in breast cancer cells." (PMID 32724475, 2020). "Interestingly, we found that the expression of the tumor-associated macrophage (TAM) markers CD68 and CD163 was higher in HER-2-positive breast cancer." (PMID 32580398, 2020). "Moreover, we observed the positive correlation between the expression of S1PR1 and CD68 and between IL-22R1 and CD68 in bone or brain metastases in breast cancer patients." (PMID 31935914, 2020). "In summary, combined high expression of CD47 and CD68 is associated with the prognosis of breast cancer, especially for hormone receptor-negative breast cancer." (PMID 31528120, 2019). "Therefore, exploring the relationship between CD47/CD68 protein and proliferation/growth factor is also essential to better demonstrate the role of CD47 and CD68 in the prognosis of breast cancer." (PMID 31528120, 2019). "In our own data, we also found that the ratio of CD163- to CD68-positive macrophages was higher in high histological and Ki67 index breast cancer, where the proportion was nearly 80% in the HR-negative subtype and only about 40% in the HR-positive subtype (data not shown)." (PMID 31528210, 2019). "In addition, combined high expression of CD47 and CD68 (CD47highCD68high) were found in 49.8% of breast cancer patients (108/217)." (PMID 31528120, 2019). "Furthermore, we also performed a systematic review of published research to clarify the clinicopathological association and prognostic significance of CD68+ and CD163+ TAMs in early stage breast cancer." (PMID 31528210, 2019). "(A) Regression of MMP-9+/CD68+ QIF scores in breast cancer TMA." (PMID 30558648, 2018).
breast carcinoma (continued). "Using CD33 and CD68 as markers for MDSCs and mature macrophages respectively, we analyzed whether they infiltrate human breast cancer tissues and which population expresses sCLU." (PMID 27405665, 2016). "We next investigated whether senescence in breast cancer subtypes correlates with differences in the recruitment and distribution of specific immune cells as assessed using CD68 immunostaining, a marker for monocytes and macrophages." (PMID 27713152, 2016). "Notably, our IHC staining of human specimens suggest that the proportions of cells with positive staining for the leptin receptor ObR, the macrophage marker CD68, and IL-8 increase as breast cancer progresses from carcinoma in situ to invasive carcinoma." (PMID 27588409, 2016). "One explanation for the difference between the presence of CD163+ and CD68+ macrophages in TS among triple-negative/basal-like breast cancer patients could be that CD68 is less expressed on mature M2 macrophages or monocytes." (PMID 22824040, 2012). "Using a publically available gene expression array dataset [GenBank:GDS806] from NCBI Gene Expression Omnibus profiles we were able to identify that breast cancer patients receiving endocrine therapy, who had recurrence, had significantly higher gene expression levels of CD68." (PMID 22824040, 2012). "Interestingly, CD68+ macrophages located in TS positively correlated with grade, tumor size and inversely correlated with luminal A breast cancer." (PMID 22824040, 2012). "Additionally, a significant positive correlation between the degree of angiogenesis and the number of CD68+ cells has been demonstrated in human breast carcinoma." (PMID 21834963, 2011). "However, few studies have examined the association between tumour CD4+/CD8+ T-lymphocytic infiltration and/or CD68+ macrophage infiltration and survival in patients with primary operable breast cancer." (PMID 18797461, 2008). "In this study, increased tumour grade and Ki-67 labelling index were associated with increased infiltration by CD68+ tumour-associated macrophages, CD4+ and CD8+ T lymphocytes and increased tumour microvessel density in patients with primary operable breast cancer." (PMID 18797461, 2008). "Risk for death due to breast cancer was not statistically significantly associated with CD68, HER2, or GRB7 gene expression in patients treated or untreated with tamoxifen." (PMID 16737553, 2006). "Positivity of macrophages only for CD163 has been found to be associated with tumor stage and lymph node status, whereas macrophage positivity for only CD68 has been associated with the molecular subtype of breast cancer, independent of other clinicopathological parameters." (PMID 41256322, 2025). "Therefore, infiltrating CD68-macrophages are associated with G3, while infiltrating CD20+ and elevated serum lymphocytes in parallel with reduced platelet and neutrophil count play a favorable role in human and canine breast cancer." (PMID 35222017, 2022). "Therefore, we used CD68 staining to examine macrophage infiltration in human breast cancer tissues." (PMID 32754259, 2020). "In addition, 24 primary breast cancers were double stained for CD68 and CXCL5." (PMID 33149188, 2020). "Second, although our study is limited as we studied a relatively small number of immune related genes and the immune microenviroment in breast cancer is complex, the recruitment of CD68 positive TAMs after a CNB raises the concern that this recruitment may occur after each breast cancer biopsy." (PMID 23741308, 2013). "Subsequently, we evaluated the impact of CD68, CD163, CD86, and PD-L1 expression in primary tumor tissues on overall survival, defined as the time from the initial breast cancer diagnosis to death." (PMID 40510346, 2025). "Specifically, the authors assessed the status of PD-L1, PD-1, CTLA-4, CD68, CD163, CD11c, iNOS, CD3, CD8, CD4, FOXP3, CD20, and Ki67 along with pan Cytokeratin and CD31 in the TME of 3098 tumors, including 587 cases with breast cancer." (PMID 40243442, 2025).
breast carcinoma (continued). "The aim of this study was to compare the expression of CD68, CD86, CD163 and PD-L1 in breast carcinomas and their paired brain metastases." (PMID 40510346, 2025). "TGFB1, ERBB2, and CD68 form a signaling network that impacts cancer progression, invasion, and resistance to therapy in HER2-overexpressing breast cancer tumors." (PMID 41373732, 2025). "The current study revealed that a combination of GEN supplementation and moderate-intensity exercise increased the M1 macrophage marker CD68 while reducing M2 macrophage markers CD163 and Arg1 in breast cancer tissue." (PMID 40604704, 2025). "This was determined by assessing the percentage area positive for pan-cytokeratin (CK), a pan-breast cancer cell marker, α-SMA; a myofibroblast marker, and CD68 as a pan-macrophage marker." (PMID 40447655, 2025). "Spatial transcriptomic data of CD68, a macrophage marker, was used to confirm this relationship, showing co-expression of ALDOA and CD68 in macrophages within both breast cancer and melanoma samples." (PMID 41239433, 2025). "Higher AF of CD163 vs. CD68 agrees with the observations in HCC, liver metastasis of colorectal cancer, and breast cancer." (PMID 38287290, 2024). "The tumor microenvironment (TME) of HR+/HER2- breast cancer cells is composed of CD3D+ T cells, CD68+ macrophages, COL1A1+ fibroblasts, and FLT1+ endothelial cells." (PMID 38892065, 2024). "Like in the case of breast cancer, the abundance of CD163+ TAMs was more predictive for overall and progression-free survival than of the CD68+ TAMs." (PMID 39451197, 2024). "According to our findings, VISTA/VSIG3/SPGL-1 proteins are expressed in breast cancer cells as well as in lymphocytes (CD45 +) and macrophages (CD68 +), both of which are immune cells that infiltrate tumors." (PMID 38833004, 2024). "In human breast cancer patients, co‐expression of SEMA7A, PDPN, and CD68 correlated with metastasis." (PMID 38426622, 2024). "In a breast cancer brain metastases model, HR+/HER2−BM compared to other BC subtypes showed a higher density of CD68+ microglia/macrophages in the tumor area and a shorter distance between PD-L1+CK+ tumor cells and PD-1+CD3+T lymphocytes." (PMID 38279145, 2024). "Others reported that high expression of CD68, CD163 and CD206 was predictive of poor OS, breast cancer-specific survival, or recurrence-free survival." (PMID 36622544, 2023). "This study demonstrates an association of concurrent high CD47 tumor cell expression and high CD68 macrophage counts with various TIL subsets, blood vessel invasion (CD31 positive), other aggressive tumor features, and interval‐presenting breast cancer." (PMID 36598153, 2023). "Our study has shown that ILC patients with low density of CD4, CD8, CD20, CD56, CD68, and FOXP3 had significantly longer DFS and OS, in contrary to TILs in TNBC and HER2‐positive breast cancer." (PMID 38151972, 2023). "In our cohorts of breast cancer patients, MALT1 expression was barely present in tumor cells but was enriched in CD68+ TAMs in breast cancer tissues with high expression cSERPINE2." (PMID 36797769, 2023). "We retrospectively included 112 patients with locoregional recurrent breast cancer, and hematoxylin–eosin staining and immunohistochemical staining (CD3, CD4, CD8, CD19, CD38, and CD68) were performed on locoregional recurrent tumor samples." (PMID 38133211, 2023). "Formalin-fixed paraffin-embedded (FFPE) humanbreast cancer tissue sections were stained for multiplex MALDI-IHCwith six photocleavable mass-tagged (PC-MT) antibodies constitutinga breast cancer antibody panel (CD20, actin-αSM, HER2, CD68,vimentin, and panCK)." (PMID 36638208, 2023). "In order to further pinpoint the role of TAMs in microcalcifications of breast cancer cells, THP-1 cells were treated with PMA and IL-4 to induce differentiation into M2-like TAM which was verified by CD68 and CD163 expression (M2-like phenotype biomarker)." (PMID 34983451, 2022).